MIR6832 (microRNA 6832)
Synonyms: hsa-mir-6832
Gene: MicroRNA gene on chromosome 6 (31,633,787 to 31,633,858, forward strand). Ensembl gene ENSG00000274494.
Homologues: Orthologues: chimpanzee MIR6832 (100% identical).